IL6 (interleukin 6)
Diseases named in the same sentence as IL6 in open-access papers (continued):
Sharing a sentence is not in itself a finding about the gene and the disease.
tumor (continued). "Ibrahim postulated that inhibiting IL6 may decrease tumor cell survival pathways, making tumor cells more susceptible to immunotherapy and chemotherapy." (PMID 38032489, 2024). "Interestingly, the STAT3-stimulating activities of IL-6 have been also recently associated to the suppression of T-cell anti-tumor activities." (PMID 39281678, 2024). "PIVKA-II and IL-6 levels are likely linked to tumor stage, as they correlated with tumor size." (PMID 38383695, 2024). "Moreover, therapeutic targeting of NCL also stimulated the tumor-infiltrated T lymphocytes, impaired cancer-associated fibroblast, and reprogrammed the tumor microenvironment via suppression of interleukin-6 in PanCa." (PMID 39410048, 2024). "Additionally, research conducted on animal studies have demonstrated the tumor-boosting function of IL-6 during the progression of colitis-associated cancer (CAC)." (PMID 39911672, 2024). "Additionally, IL-6 influences metabolic processes and is implicated in conditions like cancer, where it supports tumor growth and survival." (PMID 39015561, 2024). "In addition, the circulating concentrations of GM-CSF or IL-6 are positively associated with the infiltration of tumor-infiltrating MDSCs, as well as the levels of chemerin in the tumor, in patients with HCC." (PMID 38397901, 2024). "Notably, high expression of IL-6 has been associated with tumor differentiation, local invasion, and poorer survival among patients with GBC." (PMID 38533492, 2024). "In addition, a significant (p = 0.004) reduction in IL-11, an IL-6 associated cytokine was also was also observed, which we previously observed to be upregulated in a tumor-intrinsic setting." (PMID 38831884, 2024). "The current finding that ST6GAL1 expression is induced by IL-1β and IL-6 suggests that the inflammatory milieu associated with PDAC may act in concert with tumor-intrinsic mechanisms to promote high levels of ST6GAL1 expression." (PMID 39260693, 2024). "Interleukin-6 is a secretory protein that is particular to cancer-associated fibroblasts (CAFs) and plays a role in the dynamic interaction between tumour cells and the microenvironment that is necessary for tumour development, invasion, and metastasis." (PMID 39816318, 2024). "Chemotherapy has been shown to modulate the transcriptional programs within tumour microenvironments and an IL6-associated inflammatory network and immediate early stress response genes have been associated with poor treatment response and accelerated disease recurrence." (PMID 39341888, 2024). "In this condition, cells and molecules in TIME dynamically evolved, leading to the accumulation of immunosuppressive cells like myeloid-derived suppressor cells (MDSCs), regulatory T cells (Tregs), tumor-associated macrophages (TAMs), and pro-inflammatory factors such as IL-6, IL-10, TGF-β." (PMID 39286258, 2024). "Regarding clinical data, the IL-6 variant was remarkably correlated with tumor size." (PMID 38103126, 2024). "Intriguingly, MG1 tumors are closely associated with tumor immunity, as evidenced by increased macrophage infiltration, as well as the involvement of B cells, platelets, and cytokines such as IL-6 and interferon-gamma (IFN-γ), as illustrated by the detection of protein abundance." (PMID 38879686, 2024). "Importantly, glial-specific IL-1R deficiency was further associated with reduced Il6 gene expression in tumor tissues of GFAPCreIL-1R1fl/fl compared to control GFAPWtIL-1R1fl/fl tumor lesions." (PMID 39030280, 2024). "In HNSCC, IL-6 has been implicated in tumor development and progression." (PMID 38534979, 2024). "Furthermore, activation of the STAT3/NFκB pathway by CAF-secreted IL-6 induces CXCR7 expression in tumor cells, which has been associated with drug resistance." (PMID 39092186, 2024). "Furthermore, IL‐6 expression was more pronounced in GC patients' tumor tissues than in normal tissues and positively associated with M2 activity." (PMID 38349050, 2024).
tumor (continued). "For example, cancer-associated fibroblasts activated by cancer cells release IL-6 and granulocyte-macrophage colony-stimulating factor (GM-CSF) to induce monocytes to differentiate into M2-like TAMs, activate the immunosuppressive tumour microenvironment and promote GISTs metastasis." (PMID 39070147, 2024). "Similarly, data from another study showed high IL6 expression measured across the entire tumour and TME associated with reduced disease-free survival, and this was potentiated in patients with high PDL1-expressing tumours (n = 108)." (PMID 39766336, 2024). "Blocking IL-6 signaling has been shown to decrease the risk of organ rejection in transplantation, while IL-6-targeted therapies are being developed to impede tumor growth and enhance patient outcomes in cancer treatment." (PMID 38564670, 2024). "IL-6 has long been associated with tumour growth through the activation of the STAT3 pathway." (PMID 39516433, 2024). "The authors also reported a significant association between increased stromal IL6 and reduced influx of anti-tumour CD3+ and CD4+ T cells, and mass cytometry analysis indicted an increased presence of immunosuppressive populations in the TME of the high IL6 subgroup." (PMID 39766336, 2024). "In addition, the Bcl11b-KO tumor cells themselves exhibited high levels of senescence-associated cytokine IL6 and high NF-kB activity." (PMID 38886378, 2024). "During the development of PDAC, the expression levels of the maturation marker MHC-II and the co-stimulatory molecules CD40 and CD86 on tumor-associated DCs decrease, which can be attributed to an increase in IL-6,150 of which M2-like TAMs are an important source." (PMID 40458305, 2024). "Notably, M2-polarized TAMs are associated with more aggressive tumor phenotypes, facilitating invasion and metastasis through the secretion of cytokines like IL-6, IL-8, and IL-10." (PMID 38396722, 2024). "Well consistent with the report that serum IL-6 is a risk factor for tumor progression, we observed that IL-6 concentrations were significantly high in the patients with advanced tumors (P < 0.001), but it was not linked with Vpr (P = 0.655 for local tumor, and P = 0.944 for systemic tumor)." (PMID 38166062, 2024). "IL-6 is associated with tumor advanced stages, invasion, and metastasis." (PMID 38444674, 2024). "In particular, IL-6 was found to be associated with the tumor volume of CCA." (PMID 38881895, 2024). "Interleukin-6 (IL-6) produced by the tumor cells may predispose to constitutional symptoms such as fever and weight loss." (PMID 39720598, 2024). "Ongoing activation of inflammatory mediators like IL-6 may contribute to tumor growth caused by faulty epigenetic modifications." (PMID 38519574, 2024). "High levels of IL-6 and IL-17 were observed in collagen gels containing stromal cells and 4THM immune DLN cells, in association with augmented tumor invasion of 4THM, an effect abolished by the inclusion of Fab rabbit anti-IL-6 or anti-IL-17 antibodies into the collagen matrix." (PMID 38540350, 2024). "They mentioned that elevated serum CRP levels might be caused by tumor necrosis or local tissue damage and upregulated in response to elevated interleukin-6 levels, which promotes tumor growth by inducing multiple signaling pathways." (PMID 38791922, 2024). "Additionally, the MyD88/NF-κB signaling pathway governs the expression of various cytokines, notably IL-6 and IL-8, which are intricately linked to tumor progression and the survival of BCSCs." (PMID 38347830, 2024). "Another study shows that the adoptive transfer of MDSCs to HCC-bearing mice not only promotes HCC progression, partially by activating tumor-associated fibroblasts via IL-6/fibroblast growth factor 1 (FGF1) signaling, but also induces resistance to sorafenib treatment." (PMID 38397901, 2024).
tumor (continued). "One theory is that stromal cells or tumor-associated macrophages (TAMs) could protect tumor cells from drug-induced apoptosis via secreting interleukin-6 (IL-6) to activate signal transducer and activator of transcription 3 (STAT3) pathway of tumor cells." (PMID 38238749, 2024). "This study also aimed to describe differences in the underlying biology of tumours with high protein expression of IL6/JAK/STAT3 using TempO‐Seq transcriptional analysis in a subset of patients (n = 14) and histological scores of the tumour microenvironment (TME) in the full cohort." (PMID 37199043, 2023). "The clinicopathological features of intracerebral embolism in left atrial myxoma and its association with the progressive implantation of tumor emboli and the potential pathogenic effects of interleukin-6 and matric metalloproteinases have been reviewed previously." (PMID 37252126, 2023). "Finally, in a NASH-related HCC mouse model burdened with diethylnitrosamine and a high-fat diet, tipifarnib significantly reduced tumor nodule formation in association with decreased serum interleukin-6." (PMID 37511305, 2023). "Various PCa research studies have associated IL-6 increment with tumor aggressiveness." (PMID 37987305, 2023). "Additionally, within the TME, IL-6 signalling has been linked to tumourigenesis in numerous mouse models and human cancers by driving tumour cell proliferation, protecting tumour cells from cell death, and promoting angiogenesis and metastasis." (PMID 37441083, 2023). "In addition, IL-6 and IL-8 drive the transcription of genes encoding MMPs and drive the epithelial-to-mesenchymal transition, thereby promoting tumor invasiveness." (PMID 36945046, 2023). "Specifically, IL-6 not only plays a key role in inducing acute phase inflammation and initiating the innate immune response, but also stimulates malignant transformation, tumor progression and cachexia associated with several tumor types." (PMID 37046658, 2023). "Our recent work demonstrated a tumor microenvironment mechanism by which CAF-associated inflammatory paracrine IL6/IL8-JAK2 signaling induces BRD4 activation by phosphorylation in CRC, leading to chromatin reprogramming through increased enhancer and super-enhancer activity." (PMID 36600243, 2023). "Low expression of KLRB1 could lead to high cytokine production, and IL-6 was mostly produced by tumor cells as well as tumor-associated fibroblasts." (PMID 37520246, 2023). "Analysis of sorted MC38T/O tumor cells from Dox-treated mice showed elevated levels of Il6, β2-microglobulin (B2m), which associates with the MHC-I complex, and CD137-ligand (Cd137L), a ligand of the costimulatory receptor CD137, which is expressed on effector T lymphocytes." (PMID 37478172, 2023). "Moreover, some key cytokines mediating CRS, like IL-6, are produced by Tumour-Associated Macrophages (TAMs), myeloid-type cells found in the patient’s tumour." (PMID 37511562, 2023). "Currently, there is evidence that inflammatory cytokines and chemokines such as TNFα, IL-1β, and IL-6 may be produced by tumor cells and/or tumor-associated leukocytes and platelets and may directly contribute to malignant progression." (PMID 38137888, 2023). "Muscle-derived IL-6 released in response to exercise is associated with anti-inflammatory effects, including improved glucose uptake by immune cells, enhanced leukocyte mobilization and counteraction of tumor-induced muscle wasting." (PMID 37760634, 2023). "Moreover, tumor ECs produce immunosuppressive factors (agniocrine) that inhibit T-cell survival/activation and provoke immunosuppressive phenotypes of tumor-associated macrophages (TAMs) via IL-6, TGF-ß, and (VEGF)." (PMID 37111629, 2023). "Additionally, another study suggested that M2 tumor-associated macrophages promote tumor growth via the NF-κB/IL-6/STAT3 signaling pathway." (PMID 37759870, 2023).
tumor (continued). "In addition to its effects on immune cells associated with the tumor, considerable attention has been given to the impact of IL-6 on cancer-associated fibroblasts due to their promotion of tumor growth." (PMID 37907991, 2023). "Interestingly, recent work in multiple mouse tumor models links necroptotic signaling to the activation of IL-6 and STAT3 while apoptotic signaling was linked to STAT5 activation, matching gene expression and cell death patterns in our models." (PMID 37819938, 2023). "We also found that Rac/Cdcd42 inhibitors may promote an anti-tumor microenvironment by inhibiting the secretion of the pro-inflammatory cytokine IL-6, which is mostly produced by tumor- associated macrophages." (PMID 37397366, 2023). "Surgical stress also inhibited NK cell activity and increases the production of some of the ILs associated with cancer progression, among which the elevated level of IL-6 promotes the angiogenesis and progression of BC and IL-8 is associated with tumor recurrence." (PMID 37312019, 2023). "In addition, tumor cells promote the production and release of platelets by activating the IL-6, and excessive platelets increase the risk of vascular embolism in cancer patients." (PMID 37165423, 2023). "Since Th17 cells have also been reported to be highly associated with anti-tumor immunity, IL-6 cluster signaling may be related to anti-tumor immune responses in cancer patients treated with ICIs." (PMID 38469154, 2023). "TNF and IL-6 can cause disordered cytokine regulation and promote tumor inflammation." (PMID 37077811, 2023). "Furthermore, activated STAT3, which is associated with a poor prognosis in cancer, participates in tumor progression via IL-10 and IL-6, and tightly regulates M2 polarization and activation status." (PMID 37759870, 2023). "PMs can be switched to tumor-associated macrophages (TAMs) in ascites with pro-tumor effect by releasing various soluble mediators, including IL-6, IL-10, CCL18, CCL22, TNF-α, TGF-β, and EGF that triggers pro-tumorigenic signaling pathways in tumor cells and infiltrating leukocytes in the TME." (PMID 37932814, 2023). "Notably, in HCC, cytokine IL-6 released by tumor-associated macrophages can enhance the expansion of CD44+ CSCs." (PMID 37835585, 2023). "Analyses of key target genes involved in the tumor–bone vicious cycle showed similar patterns of gene expression in the vehicle-treated Cont-4T1 and Pth1rKD-4T1 tumors except for Il6, Ackr3 (encoding CXCR7), and Cyp19a1, which were reduced in the Pth1rKD-4T1 cells." (PMID 36692956, 2023). "Similarly to IL-6, high IL-8 concentration was shown to be associated with tumor progression, worse responsiveness to the ICI therapy and identified as an independent biomarker of poor ICI therapy outcome." (PMID 36860876, 2023). "Intriguing studies implicated that TAM-derived IL-6 supports tumor progression in several settings." (PMID 36614179, 2023). "Interestingly, in a study of 209 resected CRC samples, high IL-6 expression in tumor-infiltrating immune cells was associated with accumulation of immunosuppressive cells in the TME, such as MDSCs and Treg." (PMID 37958363, 2023). "In addition, tumor-derived IL-6 and adrenoceptor beta 3 (β3-AR) activation is associated with CAC mediated adipose tissue browning." (PMID 37205195, 2023). "Furthermore, the results showed that the downregulation of CYR61 and IL6 expression maintained a statistically significant association with the progression of individual cancer stages in LUAD tumor samples compared to their respective controls." (PMID 37887075, 2023). "Tumor-associated macrophages are known to suppress adaptive immunity through secretion of variety of chemokines and cytokines such as tumor necrosis factor-α, interleukin (IL)-1, IL-6, and IL-10 to promote tumor growth, angiogenesis, invasion, and migration." (PMID 37408277, 2023).
tumor (continued). "Additionally, PD-L1 expression levels on tumor cells were significantly increased in the IL-6-deficient mice compared with wild-type mice." (PMID 38022654, 2023). "Olfr29-ps1 is regulated by the pro-inflammatory cytokine IL6 and tumour-associated factors." (PMID 36817434, 2023). "An immunosuppressive tumor microenvironment caused by high amounts of arachidonic acid was discovered in earlier research, which was demonstrated by arachidonic acid’s decreased transcriptional responses to interferon and IL-6 in monocyte-derived macrophages." (PMID 37686118, 2023). "Lastly, IL-6 can aid in tumorigenesis by fostering chronic inflammation, cell survival, and angiogenesis, and it is involved in differentiating T cells into Th17 cells, which in certain contexts are implicated in promoting inflammation and tumor growth." (PMID 37895855, 2023). "The correlation of monocytes and IL-6 that we have shown supports our hypothesis that monocytes are associated with more aggressive tumor growth and might therefore serve as a possible prognostic biomarker in PDAC." (PMID 36672313, 2023). "Accordingly, it has been shown that the pharmacological inhibition of IL-6 trans-signaling via the administration of recombinant sgp130Fc increased tumor cell survival, proliferation, and migration, suggesting that IL-6 signaling can be associated with a better CCA prognosis." (PMID 38275386, 2023). "IL‐6 could also activate the immunosuppressive regulatory T cells, myeloid derived suppressor cells and tumor‐associated macrophages." (PMID 38020717, 2023). "Recently, IL-17-producing Tregs have been identified to be associated with tumor invasiveness and poor disease prognosis; however, Th17 cells may play anti-tumor roles along with the production of IL-6 and IL-17 as inflammatory cytokines." (PMID 36816749, 2023). "Overexpression of IL-6 is associated with tumor aggressiveness in PCa." (PMID 37987305, 2023). "Activation of STAT3 by the IL-6 secreted in head and neck squamous cancer cells in tumor-associated endothelial cells has nominated this factor to be a part of CSCs and ECs network, considering the role of IL-6 in the induction of glycolytic pathway, as a glycolytic phenotype in ECs cells." (PMID 37328876, 2023). "Most patients with IBC before neoadjuvant therapy had high levels of the proangiogenic factor VEGF (median 441 pg/ml) and the pro-inflammatory cytokine IL-6 (median 9.4 pg/ml), indicating the aggressive nature of the tumor growth and its association with inflammation." (PMID 36873124, 2023). "highlighted the similar roles of tumor-associated cytokines, such as IL-6." (PMID 37680632, 2023). "A significant source of IL-6 appears to be the tumor-associated macrophages, although HCC cells could secrete IL-6 in a YAP (yes-associated protein)-dependent manner." (PMID 37892997, 2023). "Additionally, cancer-associated fibroblasts (CAFs) actively encourage tumor angiogenesis by producing chemokines and cytokines such as IL-4, IL-8, IL-6, TNF, CXCL12, TGF, and VEGF which have anti-inflammatory and pro-angiogenic properties." (PMID 36829187, 2023). "Signalling and chronic-tumour dependent hematopoietic stimulation through the release of CSF-2, CSF-3, IL-6, and other cytokines are associated with the activation of STAT3 signalling and expression of c/EBPβ transcription factor which sustain MDSC expansion and immune suppressive features." (PMID 36161514, 2023).